IL6 (interleukin 6)
Diseases named in the same sentence as IL6 in open-access papers (continued):
Sharing a sentence is not in itself a finding about the gene and the disease.
breast cancer (continued). "IL-6 signaling has also been found to play an important role in breast cancer stem cells -or so-called mamospheres-progression and survival." (PMID 28927416, 2017). "Normal adipocytes, located far from the cancer cells, showed significantly lower frequencies of IL6 expression when compared to the adipocytes in the vicinity of breast cancer cells." (PMID 28333977, 2017). "A member of the IL-6 cytokine family, IL-11 has been found to play an oncogenic role in various malignancies, including gastric carcinoma, breast cancer, and hepatocellular carcinoma." (PMID 29100303, 2017). "Our previous study demonstrated that in breast cancers, IL-6 stimulates STAT3-dependent, nuclear factor-κB-mediated indoleamine 2,3-dioxygenase (IDO) upregulation in MDSCs; this triggers immunosuppressive effects of MDSCs in vitro and vivo." (PMID 29326716, 2017). "IL-6 has furthermore been demonstrated on the leading edge of human breast cancer specimens in vivo and has been shown to correlate positively with advanced tumor stage." (PMID 28545495, 2017). "We conclude that exposure of MDA-MB-231 and MCF-7 breast cancer cells to MH leads to inhibition of IL-6 production as well as secretion." (PMID 28856117, 2017). "Chronic inflammation has been shown to result in increased aromatase expression within mammary tissue, and increased expression of cytokines, such as interleukin (IL)-6 and IL-8, which have been shown to regulate breast cancer stem cells." (PMID 29187227, 2017). "Cisplatin-treated rats exhibited significantly increased levels of TNF-α (p < 0.001), IL-6 (p < 0.01), and IL-8 (p < 0.001) whereas, significantly decreased the level of IL-10 (p < 0.01) on the 5th day when compared with breast cancer control rats." (PMID 28420987, 2017). "The results demonstrated that Shp2 is required for the IL-6-induced EMT of breast cancer cells, and both the phosphatase activity of Shp2, and its tyrosine phosphorylation, are necessary for EMT triggered by IL-6." (PMID 28208810, 2017). "One major implication of IL-6 in breast cancer relates to observations that the acquisition of drug resistance occurs within cell populations that are able to produce higher levels of the cytokine." (PMID 28607534, 2017). "Of these inflammatory cytokines, IL‐6 is reported to play especially important roles in the development of lung and breast cancers." (PMID 28618162, 2017). "Recent studies demonstrated aberrant IL6 production and secretion in a large variety of malignant tumours, including breast cancer, ovarian cancer, lung cancer and GBM, revealing the oncogenic effects of IL6 signalling." (PMID 29258522, 2017). "We found that more MDSCs were recruited in IL-6 high-expressing breast cancer tissues, in which SOCS3 inhibition was detected." (PMID 29326716, 2017). "To assess the IL6 expression levels in human breast cancer tissues, we examined the IL6 expression by immunohistochemistry using 39 consecutive breast cancer patients." (PMID 28333977, 2017). "In TS/A mammary tumor murine model, TEXs injected into the bone marrow interacted with CD11b+ myeloid precursors, inducing IL-6 producing, Stat3 phosphorylation, and skewing bone marrow-derived cells (BMDCs) differentiation to MDSCs." (PMID 28642882, 2017). "Another study demonstrated that p16 and miR-146b-5p are down-regulated in breast cancer CAFS; p16 restitution suppresses IL-6 expression and secretion by up-regulating miR-146b-5p in breast cancer." (PMID 28851377, 2017). "In the loop, IL-6 is involved in cancer progressions, and the elevation in serum predicts poor prognosis in certain cancers, including breast cancer." (PMID 27861147, 2017). "Inhibitors targeting various components of the IL-6/JAK/STAT3 pathway have been effective in a number of preclinical models of breast cancer." (PMID 28607534, 2017).
breast cancer (continued). "We compared the correlation between the expression of IL-6 and number of infiltrated MDSCs in situ to evaluate the effects of IL-6 on MDSC accumulation in breast cancer tissues." (PMID 29326716, 2017). "For breast cancer, IL-6 seems to be a double-edged sword because it was identified as both a tumor-promoting and a tumor-inhibiting cytokine." (PMID 28591216, 2017). "Specifically, PTPRD expression in both MDA-MB-231 and MCF-7 breast cancer cells increased significantly 12 to 24 h after IL-6 treatment." (PMID 29228728, 2017). "Based on the staining intensity and extent of IL-6 expression, breast cancer patients were divided into an IL-6 low expression group (IL-6low) and high expression group (IL-6high)." (PMID 29326716, 2017). "The IL-6/JAK2/Stat3 pathway was shown to be preferentially active in CD44+CD24- breast cancer cells that harbor stem cell-like features." (PMID 28966805, 2017). "Although previous CPD study demonstrated that regiments CEF enhanced bone resorption, CPD intervention suppressed bone resorption marker, such as IL-6, and exerted bone protective effects on breast cancer-induced osteolysis." (PMID 29228681, 2017). "We also found that decreased circulating adiponectin levels and increased leptin, IL-6, IL-8, TNF-α, resistin and visfatin levels are significantly associated with risk of breast cancer." (PMID 29088874, 2017). "It has been demonstrated that high levels of IL-6 have been detected in serum of patients suffering from breast cancer." (PMID 29383101, 2017). "In conclusion, ZEB1 and ZEB2, through the induction of various cytokines, including IL‐6 and IL‐8, facilitate tumor growth both in autocrine and in paracrine manners in basal‐type breast cancer cells." (PMID 28618162, 2017). "Intriguingly, Dub3 was identified as an early response gene that was upregulated after exposure to inflammatory cytokines such as IL-6, which plays a critical role in the growth and metastasis of breast cancer cells, as well as the maintenance of breast CSCs." (PMID 29088851, 2017). "Decreased concentrations of adiponectin, and increased concentrations of leptin, IL-6, IL-8, TNF-α, resistin and visfatin were significantly associated with risk of breast cancer." (PMID 29088874, 2017). "Compared to THP-1 cells, MDA-MB-231 breast cancer cells displayed a higher basic level of IL-6 and MCP-1." (PMID 28832545, 2017). "In the patients with progressive metastatic breast cancer (n = 65) the median serum Shh and IL-6 levels were 37.96 pg/mL and 172.2 pg/mL respectively ranging from 19.10 to 58.4 pg/mL for Shh and 89.47 to 301.4 pg/mL for IL-6." (PMID 28496132, 2017). "This seems to be a major reason for the induction of metastasis, and the attraction of tumor-associated suppressive myeloid cells, endothelial, and stromal cells into the tumor, seen with increasing IL-6 levels in human breast cancer." (PMID 28545495, 2017). "Our findings identify multiple functional pathways affected by MH in human breast cancer and highlight the IL-6/STAT3 signaling pathway as one of the earliest potential targets in this process." (PMID 28856117, 2017). "ADM-resistant breast cancer cell lines also expressed more IL-6 and IL-6R than Adriamycin (ADM)-sensitive cell lines." (PMID 28388577, 2017). "It has been shown that IL-6 induces EMT in breast cancer models, and that it promotes metastasis to lymph node and lungs in HNSCC." (PMID 29245982, 2017). "In this study, we showed that exogenous and endogenous IL-6 can enhance breast cancer invasion and migration, through the promotion of EMT." (PMID 28208810, 2017). "IL-6 was suggested to play a key role in development of breast cancer malignancy such as invasion and metastasis." (PMID 28212583, 2017).
breast cancer (continued). "The role of IL6 or IL8 has been independently studied in breast cancer lines due to their different roles in tumour biology, the different cellular origins from which they can be obtained and their cancer-related inflammatory roles." (PMID 28472950, 2017). "Meanwhile, IL-6 in p16-defective cells is responsible for the paracrine pro-invasive/migratory effects of these cells on breast cancer." (PMID 28851377, 2017). "Similar results showed that PSP treatment of the acute myeloid leukemia line, HL-60 resulted in a dose-dependent increase of IL-6 release, while 24-h treatment with PSP and PHA of human PBMCs from breast cancer patients also showed increased IL-6 expression." (PMID 28932226, 2017). "Melanoma and breast cancer cells are able to release several interleukins such as IL-8 and IL-6 under pro-inflammatory conditions." (PMID 28264501, 2017). "In this study, we show that breast cancer cells increase production and secretion of IL6, IL8, CSF2 and CCL2 cytokines after withdrawal of chemotherapeutic drugs (paclitaxel, 5-fluorouracil or doxorubicin)." (PMID 28703802, 2017). "In this study, we evaluated the expression of SOCS proteins and their effects on IL-6-induced activation of the JAK/STAT signaling pathway in breast cancer MDSCs." (PMID 29326716, 2017). "For example, the study that demonstrated a KYNA-mediated induction of IL6 in breast cancer cells discussed this observation as part of the mechanisms allowing tumor cells to escape immune surveillance." (PMID 29379504, 2017). "In breast cancer, it was reported that NF-κB induced cancer progression through targeting IL-6 and IL-832,33." (PMID 29273733, 2017). "In this study, we found that exogenous IL-6 induced a significant downregulation of E-cadherin, and an enhancement of migration in the breast cancer cell line T47D." (PMID 28208810, 2017). "In conclusion, our study showed that IL-6 can enhance breast cancer invasion and migration, through the promotion of EMT." (PMID 28208810, 2017). "In this study, high IDO expression was correlated with high IL-6 expression both in breast cancer tissues and serum." (PMID 29296206, 2017). "Interleukin-6 was mainly expressed in the cytoplasm of breast cancer cells, as well as in some mesenchymal cells." (PMID 29326716, 2017). "Our findings uncover an important function that links Shp2 to IL-6-promoted breast cancer progression." (PMID 28208810, 2017). "Serum IL-6 concentrations are not only increased in more than half of all breast cancer patients but are also significantly higher in IBC patients compared to non-IBC patients." (PMID 28607534, 2017). "Though previous studies reported that IL-6 restored MDSC accumulation in a mouse model of mammary carcinoma, a few studies have focused on the relationship between IL-6 and MDSCs in human breast cancer." (PMID 29326716, 2017). "The present study showed that exogenous and endogenous IL-6 can enhance breast cancer invasion and migration, through the promotion of EMT." (PMID 28208810, 2017). "For example, a yoga intervention in breast cancer survivors reported decreases in IL-6, TNF-α, and IL-1β." (PMID 28694775, 2017). "Upstream of Stat3, Il6 tended to be highly expressed and hepatocyte growth factor (Hgf) is significantly highly expressed in mammary tumors arising in PIK3CA‐H1047R in comparison with Her‐2 transgenic mice." (PMID 28296140, 2017). "A study by Conze and colleagues showed that IL-6 is overexpressed in multidrug resistant breast cancer." (PMID 28754000, 2017). "We found that in primary breast cancer tissues, cancer-derived IL-6 was positively correlated with infiltration of MDSCs in situ, which was accompanied by more aggressive tumor phenotypes and worse clinical outcomes." (PMID 29326716, 2017). "The correlation between IL‐6 production and cancer proliferation has been reported in various types of cancers, including lung, prostate, and breast cancers." (PMID 28618162, 2017).
breast cancer (continued). "Collectively, these results suggest that long-term exposure of breast cancer cells to IL-6 can induce an EMT phenotype." (PMID 28208810, 2017). "Serum level IL-6 has been identified as prognostic marker in many types of cancer, including ovarian cancer, prostate cancer, breast cancer, colon cancer, melanoma and HNSCC." (PMID 29245982, 2017). "As expected, stimulation with TNFα increased the expression levels of the investigated cytokines in MDA-MB-231 breast cancer cells significantly compared to unstimulated control (IL-6 4-fold, IL-8 6-fold, MCP-1 5-fold)." (PMID 28832545, 2017). "Although over twenty adipokines are known; only twelve (adiponectin, leptin, IL-6, TNF-α, HGF, PAI–1, resistin, secreted frizzled-related protein 5 (SFRP-5), lipocalin 2, IL-8, apelin and visfatin) have been implicated in breast cancer." (PMID 29088874, 2017). "Exposing HeLa cervical cancer cells and MCF-7 breast cancer cells to IL-6 also repressed miR-204 expression." (PMID 28388577, 2017). "In breast cancer, hypoxia inducible factor (HIF1α) induction can enrich the breast cancer stem cell population via interleukin 6 (IL6) and IL8 activation of ABCB1." (PMID 29117122, 2017). "MCP-1 and IL-11 are stimulators within the development and progression of breast cancer, while IL-6 takes part in survival, proliferation, and cell migration processes." (PMID 28763032, 2017). "For example, studies indicate that IL-6-174G>C are correlated with altered breast cancer survival of different race and hormone status." (PMID 28548958, 2017). "In the current study, the human breast cancer cell line T47D was treated with exogenous IL-6, for 72 h." (PMID 28208810, 2017). "Strong evidence of a functional link between inflammation and breast cancer cell transformation has been shown to be mediated by the activation of NF-κB signalling, increased IL-6 and STAT3 phosphorylation by Iliopoulos and collegues." (PMID 28416734, 2017). "Twenty fresh breast cancer tissue samples were collected to study the correlation between RNA levels of tumor-derived IL-6 and percentages of CD45+CD33+CD13+CD14−CD15− MDSCs in breast cancer tissues by flow cytometry analysis." (PMID 29326716, 2017). "The findings uncover an important function that links Shp2 to IL-6-promoted breast cancer progression." (PMID 28208810, 2017). "In this study, an IL-6-induced EMT model of breast cancer was established by the overexpression of IL-6 in T47D cells." (PMID 28208810, 2017). "Similar to other solid malignancies, elevated IL-6 expression in breast cancer positively correlates with increased tumor stage, lymph node involvement, recurrence risk, and distant metastasis." (PMID 28607534, 2017). "Based on the median relative RNA level of IL-6, breast cancer samples were divided into IL-6high and IL-6low groups." (PMID 29326716, 2017). "To further evaluate the relationship between the expression of these cytokines and stem-like cell properties, we used the MDA-MB-231 cell line, a basal-type breast cancer cell line, and confirmed that these cells constitutively express IL6 and IL8." (PMID 28472950, 2017). "It has been demonstrated that KYNA ligated to AhR induced IL6 mRNA expression in breast cancer cells." (PMID 29379504, 2017). "IL-6 was unaltered in breast cancer but significantly increased in dense breast tissue, whereas IL-6RA was increased in both tissues." (PMID 29387062, 2017). "Mechanistically, CUR pre-treatment ameliorated the cisplatin-induced nephrotoxicity by inhibiting the pro-inflammatory cytokines like TNF-α, IL-6, IL-8, and augmenting anti-inflammatory cytokine (IL-10) in mammary tumor bearing rats." (PMID 28420987, 2017). "Previous studies have also demonstrated elevated cytokine levels in primary human breast cancers, such as IL-6 and IL-8." (PMID 28402277, 2017). "CCL-19 and -24, CXCL-1 and -10, and IL-6 were increased in dense breast tissue only, whereas IL-18BP was increased in breast cancer only." (PMID 29387062, 2017).
breast cancer (continued). "Our findings indicated that ZEB1 and partly ZEB2 regulated the characteristic inflammatory phenotype of breast cancer cells, in part through IL‐6 and IL‐8." (PMID 28618162, 2017). "Our results suggest that breast cancer cells stimulate adjacent adipocytes via paracrine manner to express and secrete IL6 in breast cancer." (PMID 28333977, 2017). "Overexpression of both IL-6 and its receptors (IL-6R and sIL-6R) is common in breast carcinoma, oral squamous cell carcinoma and prostate cancer." (PMID 28927416, 2017). "Given that IL-6 and IL-8 cooperate to enhance migration in breast carcinoma cells, we sought to investigate their potential role in metastasis by inhibiting their cognate receptors using Tocilizumab and Reparixin." (PMID 28548090, 2017). "Another study suggested that carriers of high-expression alleles of IL6-174 and TNF-308 were associated with poorer memory in breast cancer patients." (PMID 27701469, 2016). "Here, we confirmed the elevation of IL6 expression in HER2-positive breast cancer cells with acquired resistance to long-term lapatinib treatment." (PMID 27694691, 2016). "We also demonstrated that elevated levels of IL-6 can be detected in the breast cancer cells after radiation." (PMID 27462787, 2016). "In breast cancer, elevated serum IL-6 correlates with poor patient survival, and IL-6 expression induction in ER-positive breast cancer cells confers an epithelial-mesenchymal transition (EMT) phenotype." (PMID 27609180, 2016). "Treatment with TGF-β, EGF, and TNF-α after IL-1β further increased IL-6 expression in MCF7_TG2 breast cancer cells." (PMID 27609180, 2016). "Because of the reliance of disease progression on a variety of IL-6–related mechanisms in breast cancer, the IL-6 signaling pathway is an ideal target for drug development." (PMID 26840088, 2016). "Our findings indicate that luminal-type breast cancer cells acquire the ability to produce IL-6 through cancer cell TG2 overexpression and IL-1β from the tumor microenvironment." (PMID 27609180, 2016). "IL-6 was widely expressed in breast cancer and was involved in growth, metastasis of cancer cells, and renewal of cancer stem cells." (PMID 27231908, 2016). "In a previous study, we found that interleukin-6 (IL-6) production was increased in acquired lapatinib-resistant HER2-positive breast cancer cells." (PMID 27694691, 2016). "Meanwhile, recent studies have identified IL-6 as a prognostic factor in the treatment of breast cancer." (PMID 27231908, 2016). "Recent report showed that IL-6 activated Notch3 signaling also induced CD133 overexpressing cells in breast cancer and further investigations are warranted." (PMID 27489358, 2016). "In this review, we evaluate the evidence regarding potential use of IL-6 antagonists for breast cancer therapy and prevention." (PMID 26840088, 2016). "MSC-secreted IL-6 has been found to act as a paracrine factor to sustain breast cancer cell migration." (PMID 27531897, 2016). "IL-6 levels were detected in culture supernatants 12 h after treatment, revealing that IL-6 concentrations peaked at from 48 h to 72 h in MCF7_TG2 breast cancer cells." (PMID 27609180, 2016). "Further evidence revealed that the growth of HER2-positive breast cancer in vivo was dependent on the HER2/IL-6/STAT3 signaling pathway." (PMID 26840088, 2016). "The transcription factor HOXB13 enhances progression and recurrence of breast cancer by down-regulation of ERα and up-regulation of IL-6 expression." (PMID 26840088, 2016). "In recent years, the treatments of breast cancer focus on the identification of cytokines as prognostic factors, including several interleukins (IL-1, IL-6, IL-10), transforming growth factor-β (TGF-β), tumor necrosis factor-a (TNF-a) and so on." (PMID 27231908, 2016). "IL-6 is elevated in HER2-positive breast cancer where IL-6 activated STAT3 and induced an autocrine loop of IL-6/STAT3 expression." (PMID 26840088, 2016).